MYCN (MYCN proto-oncogene, bHLH transcription factor)
Diseases named in the same sentence as MYCN in open-access papers (continued):
Sharing a sentence is not in itself a finding about the gene and the disease.
retinal tumours (1 paper, 2024). "Chickens that were hatched with stable retinal MYCN expression, formed retinal tumours with metastatic growth that infiltrated the sclera and optic nerve and formed extraocular tumours within 6–9 weeks." (PMID 37606819, 2024).
sarcopenia (1 paper, 2021). Progressive decline in muscle mass due to aging which results in decreased functional capacity of muscles. "Using a simple regression analysis, sarcopenia, unfavorable tumor histology, MYCN+, and NB2004-HR chemotherapy were significant risk factors for 5-year mortality." (PMID 34490339, 2021).
small-cell prostate carcinoma (1 paper, 2023). "It has been postulated that differentiated NE-like cells may progress to small-cell prostate carcinoma (SCPC) through the accumulation of additional genetic alterations, such as loss of RB1, MYCN, and AURKA amplification." (PMID 37740039, 2023).
staphylococcus aureus infection (1 paper, 2025). An infectious process in which the bacteria Staphylococcus aureus is present. "On the other hands, the pathway of Staphylococcus Aureus infection highly enriched in CD82 and MIOX, the pathway of proteasome highly enriched in CDKN1A and MYCN." (PMID 39966875, 2025).
Ta (1 paper, 2024). "In Ta tumors, the most frequent gene variants were FGFR3 (48%) and PIK3CA (26%), and the most common amplifications were AKT1 (24%), FGFR3 (13%), MYCN (11%), and CCND1 (11%)." (PMID 39410541, 2024).
tumor (1,481 papers, 1988 to 2026). "Understanding its complex biology is critical for the development of novel immunotherapies aimed at restoring effective anti-tumor immune responses, particularly in high-risk MYCN-amplified NB." (PMID 41936749, 2026). "While multiple features stratify NBL patients into the high-risk category, MYCN amplification in the tumor is well established as the major factor leading to classification of a patient as having high-risk disease." (PMID 41539997, 2026). "Although MYCN amplification is a well-established marker of high-risk disease, its interplay with the tumor immune microenvironment-particularly tumor-associated macrophages (TAMs)-remains poorly understood." (PMID 41993132, 2026). "Previous studies have identified MYCN amplification as a key factor strongly associated with tumor relapse and aggressive growth." (PMID 40708972, 2025). "Dysregulation of MYCN is implicated in various malignancies, influencing tumor initiation, progression, and therapeutic response." (PMID 40593489, 2025). "Classification into risk groups is based on factors such as the patient’s age, tumor stage, histological features, and MYCN oncogene amplification, a key driver of aggressive disease behavior." (PMID 39860532, 2025). "Both glycolytic and ketolytic genes were associated with MYCN amplification when compared to MYCN non‐amplified tumours." (PMID 41420301, 2025). "In aggressive childhood cancer, neuroblastoma, NDRG1 is considered to be a tumor suppressor, with its low expression being significantly associated with prognostic factors such as primary tumor size, MYCN amplification, and poor prognosis." (PMID 40378957, 2025). "In regard to DPI, we previously demonstrated that low micromolar concentrations effectively reduced tumor growth and metastasis in a MYCN-driven zebrafish model of NB, with low associated toxicity." (PMID 41211440, 2025). "At the same time, the MYCN gene is strongly linked to patient prognosis, and increased MYCN expression leads to tumor recurrence and a bad prognosis." (PMID 40969276, 2025). "This analysis revealed that MYCN amplification was strongly associated with the significantly reduced tumor infiltration of T cells, NK cells, myeloid dendritic cells, and monocytic lineage cells." (PMID 39860532, 2025). "Alternately, tumour suppressive miRNAs are also associated with MYCN in mutually repressive feedback loops." (PMID 40779030, 2025). "MYCN gain and the activating P44L mutation were again associated with a significantly stronger response to MYCi975 compared to other tumor organoids." (PMID 39740515, 2025). "MYCN is one of the most important regulators of cell proliferation and its amplification is associated with more aggressive tumor types, which makes it the most important stratification factor while evaluating NB risk groups." (PMID 39101440, 2024). "Somatic mutations in MYCN have been identified across various tumors, playing pivotal roles in tumorigenesis, tumor progression, and unfavorable prognoses." (PMID 38884091, 2024). "Inhibition of the elevated rate of translation with a small molecule inhibitor is a promising strategy for suppressing MYCN‐dependent tumor growth and is reportedly effective for controlling the high‐risk MYCN‐driven NB." (PMID 37975412, 2024). "For example, the patients with heterogeneously MYCN-amplified tumours were less likely to have unfavourable features such as loss of heterozygosity (LOH) at chromosome arm 1p." (PMID 39715281, 2024). "Nearly half of high-risk NBL patients carry amplification of the MYCN oncogene, a broad transcriptional activator that regulates multiple aspects of the tumor immune interaction." (PMID 39199637, 2024). "Implantation of each group into immune-deficient mice led to tumor development of MYCN and JMJD6/MYCN groups." (PMID 38488852, 2024).
tumor (continued). "While methylation alterations at MIR886 show a slightly weaker association with increased hazard in MYCN amplified NB tumours, methylation alterations at this region were found to be strongly associated with increased hazard in NB tumours with 11q deletion." (PMID 39217334, 2024). "MiR-204 is known as a tumor suppressor that targets multiple oncogenes, including MYCN, BCL2, NTRK2 and PHOX2B, which are associated with tumor progression and chemoresistance in NB." (PMID 39594898, 2024). "These include age at diagnosis, tumor stage and differentiation, tumor histology and associated DNA ploidy, MYCN status, and chromosome 1p and 11q copy number status." (PMID 39097671, 2024). "Prognosis involves several factors such as age at diagnosis, tumor location, and genetic testing to identify NB-associated segmental chromosomal aberrations and mutations, especially in MYCN and Anaplastic Lymphoma Kinase (ALK)." (PMID 39101440, 2024). "Here, we used a human embryonic stem cell (hESC)-based model to experimentally dissect the links between NB-associated CNAs, MYCN amplification, and tumour initiation." (PMID 38702304, 2024). "MYCN's role in tumor development differs in low‐risk or highly differentiated tumors compared to HR (MYCN‐amplified) tumors where MYCN induces dedifferentiation and proliferative activation." (PMID 40625458, 2024). "We found that MYCN overexpression was associated with the sensitivity of tumor cells to ceftriaxone treatment." (PMID 37975412, 2024). "MYCN amplification is one of the most common events associated with NB tumorigenesis, providing many reasons to focus on tumor-specific MYCN dependency and to target this entity as an effective treatment for NB." (PMID 39594793, 2024). "A key driver of high-risk disease, MYCN amplification has been strongly associated with tumor immune escape and adverse prognosis relative to low-risk disease." (PMID 39668192, 2024). "Loss of one functional allele of Runx1t1 (Runx1t1+/−) almost completely abolished tumor development in Th-MYCN+/+ homozygous mice." (PMID 38992040, 2024). "MYCN-T58A is MYCN with the oncogenic mutation in T58 that increases the stability of the Myc protein and produces robust tumour growth." (PMID 37606819, 2024). "One of the prominent molecular features of the NB is MYCN amplification, which is linked to aggressive tumor growth and poor prognosis, along with an increase of chromosome 17q." (PMID 38601081, 2024). "This association has been observed in the presence of MYCN amplification, unfavourable tumour histology, and in patients older than 18 months of age." (PMID 38398114, 2024). "CCNB1IP1 was upregulated in MYCN‐amplified (MYCN‐AM) NB cell lines and patients‐derived tumour tissues, which was associated with poor prognosis." (PMID 37461251, 2023). "It is a remarkably heterogeneous disease with a clinical course that varies greatly depending on several risk-stratification factors (including age, stage, tumor histology, and amplification of the MYCN oncogene)." (PMID 37183823, 2023). "It inhibits cancer cell proliferation and increases necrosis.MYCN proto-oncogenes regulate cell growth, apoptosis and differentiation and are associated with tumor aggressiveness and chemoresistance." (PMID 37415742, 2023). "Further, in approximately 2% of patients, RB develops without any RB1 alterations and is instead driven by oncogenic amplification of MYCN on chromosome 2, which is also associated with aggressive tumor behavior." (PMID 37239954, 2023). "On the basis of INSS and INRGSS, Children’s Oncology Group (COG) risk stratification system, including age of diagnosis, MYCN status, DNA ploidy, tumor histologic classification and INSS/INRGSS stages, was following established." (PMID 37633889, 2023). "The combination of stiffness and RA treatment enhanced NB differentiation and reduced proliferation and tumour markers such as MYCN (a gene linked to NB high-risk prognosis)." (PMID 37887559, 2023).
tumor (continued). "MYCN is a molecular hallmark of this tumor, thereby justifying the significance of the other four markers." (PMID 37297004, 2023). "Unlike NXS2, the 9464D model has similar characteristics to human HR-NB, with a low tumor mutation burden, overexpression of MYCN, and aberrant expression of MHC-I, whereby only about 25% of 9464D are capable of MHC-I induction upon IFN-γ stimulation." (PMID 37835389, 2023). "Decreased KRT19 expression was significantly associated with NB tumor progression, MYCN expansion, and poor prognosis." (PMID 36874032, 2023). "The upregulation of NANOG and BMI1 expression was associated with increased MycN expression, as well as the elevated spheroid growth and tumor-initiating capacity of NB cells, in mice." (PMID 36980635, 2023). "There are many recurrent genetic aberrations in NB, arguably the most important being amplification of the MYCN oncogene, which has been reported in around 25% of NB and classifies tumours as high-risk." (PMID 37958407, 2023). "In line with this possibility, poorly differentiated cells in MYCN-amplified RB have been shown to be more responsive to chemotherapy than differentiated tumor cells in RB1-deficient RB with featured rosettes." (PMID 36726110, 2023). "Approximately 78% of the globally downregulated circRNAs in MYCN-amplified high-risk tumor samples were upregulated by DHX9 knockdown in our cell model." (PMID 37402719, 2023). "Our finding also provides plausibility for predicting the risk of tumour progression and provides additional insight for drug development and refinement of individualized treatment regimens for high‐risk NB based on MYCN and CCNB1IP1 protein interactions." (PMID 37461251, 2023). "INRG stage, in addition to patient age, MYCN amplification status, and tumor biology, dictate risk status." (PMID 36832517, 2023). "A clonal nonsense driver mutation in SETD2 was lost at relapse, and several subclonal variants were observed in ALK and MYCN in <5% of the tumor cells, which is often observed in highly amplified oncogenes." (PMID 36867694, 2023). "The best possible strategy for limiting tumor cell growth caused by MYCN alterations would be to target MYCN directly." (PMID 37046804, 2023). "Elevated total cfDNA levels in the plasma indicated a heavier tumor burden, associated with tumor staging, MYCN amplification (MNA), primary tumor sites, and tumor metastasis." (PMID 35632981, 2023). "- Tumor biology: Certain genetic abnormalities, such as MYCN amplification, are associated with a higher risk of relapse and poorer outcomes." (PMID 37206500, 2023). "One MYCN-amplified tumor displayed complete RB1 loss (RB1–/–), caused by a germline frameshift on exon 5 followed by loss of heterozygosity." (PMID 36245757, 2022). "The pre-therapy 18F-FDG PET/CT radiomics is able to predict MYCN amplification and 1p and 11 aberrations in pediatric NB, thus aiding tumor stage, risk stratification and disease management in the clinical practice." (PMID 35372427, 2022). "Accordingly, cfDNA from liquid biopsies and DNA from matched tumour samples of high-risk NB patients were collected and used to detect MYCN amplification and actionable ALK genetic alterations." (PMID 36362869, 2022). "Specifically, analysis of extensive tumor collections confirmed the prevalence of three key mutational driver types in HR-NB, namely MYCN amplification, ATRX inactivation, and rearrangement of the TERT promoter." (PMID 36030273, 2022).
tumor (continued). "The tumor sample with the MYCN-amplified RB1-deficient (MYCNARB1–/–) background clustered within another subbranch in branch 1 and separated from MYCNARB1PRO tumors." (PMID 36245757, 2022). "In NB, MIF expression has been reported to be associated with tumor progression, immune evasion, inflammation, expression of pro-angiogenic factors, and MYCN oncogene." (PMID 35715791, 2022). "The prognosis for high-risk patients is extremely poor, including children with MYCN-amplified tumors, unfavorable tumor biology and/or the presence of distant metastasis." (PMID 35814452, 2022). "This is consistent with the cell of origin being similar for RB1-deficient and RB1-proficient, MYCN-induced neoplasms." (PMID 35729105, 2022). "Two patients had divergent MYCN results, potentially resulting from the heterogeneity of the tumor or underestimation of the mutational burden by biopsy bias." (PMID 36353561, 2022). "In this study, we analyzed publicly available NB patient data sets and revealed that EIF4EBP1 is overexpressed in NB compared to normal tissues, is significantly co-expressed with MYCN, and is elevated in high-risk relatively to low-risk tumor groups." (PMID 35379801, 2022). "NK EVs have been shown to be enriched in the tumor suppressor miR-186, which was downregulated in MYCN-amplified neuroblastoma cell lines and in tumor lesions from high-risk patients vs. low-risk patients." (PMID 36498469, 2022). "Patients with risk factors like age >18 months, high tumor stage, MYCN amplification (MNA), segmental chromosomal aberrations, and/or unfavourable histology fall into the high-risk group with poor prognosis." (PMID 36037157, 2022). "MYCN amplification can affect all tumor cells (homogenous MYCN amplification, homMNA), which consequently is associated with a poor prognosis." (PMID 35804856, 2022). "In a recent clonal analysis of tumor samples, the amplification of MYCN occurs in ~ 20 to 30%, ATRX mutations or deletions in ~ 10%, TERT mutations in ~ 10%, and MDM2-CDK mutations in ~ 2% of HR-NB." (PMID 36030273, 2022). "South Africa has a higher-than-average number of patients with high-risk tumours (75.6%), mainly because of advanced disease (70%) and a 54% MYCN amplification of tumours." (PMID 36140541, 2022). "Medical science needs to make many other efforts to overcome the issue linked to aggressive tumor and target therapy, especially in the field of genes and transcription factors such as MYCN." (PMID 36139583, 2022). "Among these factors, MYCN proto-oncogene amplification, which is detected in about 20–30% of NB, is considered as the most reliable genomic hallmark of aggressive tumor behavior and treatment failure." (PMID 35169131, 2022). "This study confirms the impact of IDRF status at diagnosis as it can be clearly correlated with other risk factors, such as a high level of NSE, MYCN amplification status, large tumor size, incomplete tumor resection, and an unfavorable outcome." (PMID 36360435, 2022). "A tumor diameter larger than 13 cm and MYCN gene amplification were found to be two independent risk factors for high-risk tumor rupture and bleeding." (PMID 36431102, 2022). "This MYCN-MV method, as an adjunct of the standard diagnostic procedures, holds potential for the rapid determination of tumor MYCN status in order to immediately start the appropriate treatment according to the INRG classification risk group." (PMID 35681607, 2022). "As a result, it's thought that removing extrachromosomally amplified MYCN in NB is linked to tumor cell reversion." (PMID 35614494, 2022). "In NB, MYCN-amp is associated with other adverse prognostic factors, including unfavorable histology, mitosis karyorrhexis index and a diploid/tetraploid tumor." (PMID 35681607, 2022).